KDR (kinase insert domain receptor)
Diseases named in the same sentence as KDR in open-access papers (continued):
Sharing a sentence is not in itself a finding about the gene and the disease.
tumor (continued). "Vascular endothelial growth factor (VEGF) is a most powerful tumor angiogenesis factor, which can interact with its cognate receptors, KDR/Flk-1 and Flt-1 to promote the growth of new blood vessels." (PMID 25984608, 2015). "VEGFR-2/KDR strongly promotes tumor angiogenesis, and active immunization against VEGFR-2/KDR has been reported to inhibit tumor growth and metastasis." (PMID 25502982, 2015). "VEGFR2 (also FLK-1 and KDR), which is highly expressed on proliferating endothelial cells of the tumor vasculature, has also been the focus of numerous pre-clinical studies." (PMID 26510973, 2015). "VEGF regulates multiple aspects of tumor angiogenesis through two high-affinity receptor tyrosine kinases, VEGFR1 (Flt-1) and VEGFR2/KDR (Flk-1), on endothelial cells." (PMID 25009649, 2014). "VEGF, as a key factor for angiogenesis and tumor growth, exerts its functions mainly through activation of 2 tyrosine kinase receptors: VEGFR-1 (Flt 1) and VEGFR-2 (KDR)." (PMID 24385810, 2013). "Several pieces of evidence have suggested that gangliosides also modulate tumor angiogenesis by controlling the activation of VEGF receptors FLT1 (VEGFR-1) and FLK1/KDR (VEGFR-2)." (PMID 24709879, 2013). "Immuno-histochemical (IHC) analyses of these sections revealed that the tumour cells themselves expressed various angiogenic markers like PECAM, VE-Cadherin, VEGF, VEGF165, NRP-1 and VEGFR-2 (FLK1/KDR) (Figure." (PMID 23185562, 2012). "Endothelial VEGF receptors, particularly VEGF receptor 2(KDR/Flk-1) has been reported to initiate critical signaling pathways through interaction with VEGF, leading to tumor angiogenesis." (PMID 21253017, 2011). "Cells in IH tumor spheres express GLUT1, indicative of an IH cell of origin, elevated levels of VEGF, and various stem/progenitor cell markers such as SALL4, KDR, Oct4, Nanog and CD133." (PMID 22192404, 2011). "The VEGFRs, particularly VEGFR-2 (KDR, Flt-1), play important roles in regulating tumor angiogenesis by promoting endothelial cell proliferation, survival and migration." (PMID 20838437, 2010). "Vascular endothelial growth factor (VEGF) and its receptor, VEGFR-2 (Flk-1/KDR), play a key role in tumor angiogenesis." (PMID 19545394, 2009). "A positive immunoreaction for KDR, ET-1, VEGF-A, and ETBR in the tumour cells was present in a varying number of samples." (PMID 15841074, 2005). "To date, we have been unable to detect Flk-1/KDR in 4T1 and MDA-MB-231 tumour cells using immunocytochemistry and Western blotting." (PMID 15655556, 2005). "Having demonstrated that murine 4T1 and human MDA-MB-231 tumour cells express NP-1 and endothelial cells (HUVEC's) express both NP-1 and KDR, we studied the effect of anti-NP1 and anti-KDR peptides on apoptosis." (PMID 15655556, 2005). "The cell type-specific markers we used for cell annotation were as follows: T cell (CD3D); NK cell (KLRD1 and NKG7); plasma cell (IGKC and JCHAIN); Mast cell (KIT and TPSB2); tumour cell (CA9, NDUFA4L2 and SLC17A3); endothelium (PECAM1, PTPRB and KDR); mesangial cell (ACTA2 and PDGFRB)." (PMID 40830065, 2025). "The top negative DEGs, including ABCB1, SPRY1, EREG, PIK3R1, SPTBN1, VIM, KDR, and others, exhibit a negative correlation with tumor purity while demonstrating a strong positive correlation with T‐cell infiltration, especially CD8+ T cells." (PMID 40567015, 2025).
tumor (continued). "In addition, cluster 25 relates to the regulation of VEGF-induced migration, including the expression of key VEGF-related genes (NRP1, NRP2, FLT1, KDR, PGF), which can promote tumour dissemination by supporting the invasion of malignant cells into the stroma." (PMID 38331751, 2024). "Furthermore, VEGFA, KDR, CXCR1 and CXCR2 were significantly upregulated in tumour samples compared with paired normal samples, except for VEGFB, whose expression was not statistically significant." (PMID 38426619, 2024). "We next evaluated the relationship between baseline CD8 infiltration (assessed by the mRNA expression level of CD8A), pretreatment tumor CD274 (PD-1 ligand 1) and KDR mRNA expression levels, and the T cell-inflamed gene expression profile of 15 biomarkers and the response to treatment." (PMID 38584166, 2024). "Analysis based on tumour grade using the UALCAN portal revealed specific expression patterns such as increased VEGFA expression in grade 2 and grade 3 tumours, elevated VEGFB expression in grade 3 tumours and high KDR expression in grade 4 tumours." (PMID 38426619, 2024). "Moreover, PGD2 inhibits tumor angiogenesis and promotes tumor cell necrosis by downregulating the expression of vascular endothelial growth factor (VEGF) as well as its receptors FLT-1 and FLK/KDR." (PMID 38704736, 2024). "As cRCC is a highly vascular tumor, over the past years, the treatment of RCC has been focused on the inhibition of VEGFA/KDR signaling pathway with an increasing number of new drugs, including tyrosine kinase inhibitors as well as anti-VEGFA humanized monoclonal antibody." (PMID 39000466, 2024). "Isolated from Sorbariasorbifolia, TTF1, also known as 5,2′,4′-Trihydroxy-6,7,5′-trimethoxyflavone, has showcased its capacity to inhibit tumor angiogenesis elicited by HepG-2 cells via reducing the VEGF, KDR, bFGF, COX-2, and HIF-1α levels of RNA and protein in key factors regulating angiogenesis." (PMID 38611849, 2024). "Strategies to block VEGF/KDR signaling have been successfully used to inhibit experimental tumor growth and indicate that KDR is the prime signaling VEGF receptor involved in the proliferating tumor endothelium." (PMID 37114147, 2023). "VEGFR2/KDR is more widely distributed and expressed in all blood vessels at endothelial contact sites and, therefore, could be found in tumor vasculature." (PMID 37803932, 2023). "Eight cases with tumor depth >10 mm showed mutations in CSF1R, ERBB4, FLT3, KDR, and NPM1, regardless of lymph node metastasis." (PMID 36780540, 2023). "As evidenced by sequencing the tumor samples acquired after re-operation, we found two cases with the activation of proangiogenic pathways, including amplifications in KIT, FGFR, PDGFR, or KDR, and they exhibited the longest PFS." (PMID 36698900, 2022). "KDR immunoreactivity was detected in blood vessel endothelium and in SCC tumor cells." (PMID 35878392, 2022). "KDR, a kinase insert domain receptor of the VEGF, could regulate tumor progression and angiogenesis." (PMID 36118855, 2022). "The present study examined mRNA and protein expression of VEGF-A, PLGF, and their receptors KDR and Flt-1 in feline CSCC and NHS controls, testing the prediction that these mediators of tumor angiogenesis would be elevated in cutaneous carcinoma relative to normal skin." (PMID 35878392, 2022). "Furthermore, PTK7 regulates the activity of kinase insert domain receptor (KDR) and thereby participates in VEGF induced tumor angiogenesis." (PMID 34367983, 2021).
tumor (continued). "Tumor hypoxia represents a potent stimulus for continued induction of several key angiogenic cytokines, including the vascular endothelial growth factor (VEGF) and its endothelial-specific receptors VEGFR1 (Flt1) and VEGFR2 (KDR/Flk1)." (PMID 33999935, 2021). "The tumor sample from one pazopanib‐responsive patient had alterations in FGFR1, KIT, and KDR, while the other had no alterations in genes associated with pazopanib activity." (PMID 34269527, 2021). "Genes related to cancer pathways were downregulated upon atezolizumab treatment, including angiogenic factors for tumor vascularization (TNK1, AREG and KDR), proto-oncogenes (RET and MET) and tumor cell survival/migration/invasion (CDH1, RARA, WNK2, WNT4A, WNT9A, TGFB2, EGF, and LAMA3)." (PMID 32616706, 2020). "When specifically binding to VEGF, it prevents VEGF from interacting with VEGF receptors on the surface of endothelial cells (Flt-1 and KDR) and blocks the VEGF-mediated pathway, which leads to suppression of vascular endothelial cell proliferation and tumor angiogenesis." (PMID 31684985, 2019). "The main mediators of tumour angiogenesis are both the two VEGFA isoforms, that is, the soluble VEGF121 and VEGF165, although the principal signalling tyrosine kinase receptor is the VEGF receptor 2 (VEGFR‐2; FLK, KDR in humans)." (PMID 31369203, 2019). "NRP1 and KDR expression was evaluated by manually scoring the frequency of dots in the tumor samples, with 0 for none detected, up to 3 for strong expression." (PMID 30027561, 2018). "Although the expression of six endothelial differentiation marker genes (PECAM1, vWF, FLT1, FLT4, KDR, CDH5) was significantly lower in normal and tumor ADSC, there was significantly greater expression of PDGFRB in ADSC when compared to BEC and NORMA1 MEC cells." (PMID 26968831, 2016). "The tumour from patient #2 presented variable 5–10 fold amplification across 4q12, which included the tyrosine kinase KIT, and tyrosine kinase receptors PDGFRA and KDR (VEGFR2)." (PMID 27843499, 2016). "POSTN promotes tumor progression and angiogenesis mediated by the VEGF receptor Flk-1/KDR." (PMID 27708222, 2016). "To obtain further insight into tumor vascularization and VEGFR expression by cancer and non-tumor cells, we used real-time qRT-PCR to quantify species-specific mRNAs of PECAM1/CD31, ENG/CD105, FLT1/VEGFR1, KDR/VEGFR2 and VEGFA genes in a large series of 150 xenografts from different tumor types." (PMID 24625025, 2014). "In addition, MR activation attenuates the expression of the VEGF receptor 2/KDR, possibly dampening the activation of a VEGFA/KDR dependent signaling pathway important for the survival of tumor cells under hypoxic conditions." (PMID 23555666, 2013). "Interestingly, artesunate also inhibits tumor angiogenesis by downregulation of VEGF, KDR/flk-1, Flt-1, NF-κB, and MMPs." (PMID 24223058, 2013). "For example, KDR expression by itself was not significantly altered between tumor and normal samples, but co-expression of KDR with VEGFC, NRP1, and PLXNC1 was associated with tumors." (PMID 23667446, 2013). "PKC-β1, PKC-β2 and VEGFR-2/KDR were overexpressed in MPM cell lines and MPM tumor tissues." (PMID 21383961, 2011). "The smallest of the VEGF isoforms, VEGF121 binds to two receptors designated VEGFR-1 (Flt-1/FLT-1) and VEGFR-2 (Flk-1/KDR), both of which are over-expressed on the endothelium of tumor vasculature but virtually undetectable in the vascular endothelium of adjacent normal tissues." (PMID 21849059, 2011). "VEGF and its receptor, VEGFR-2 (Flk-1/KDR), play a key role in tumor angiogenesis." (PMID 19545394, 2009). "When we analysed blood samples from patients with a high tumor burden, i.e., metastatic NSCLC, we found significantly elevated gene expression levels of CD34 and KDR which may indicate an elevated number of CEC." (PMID 18755033, 2008).
tumor (continued). "On the other hand, anti-VEGF treatment probably has direct effects on tumour cells of CC-RCC because these cells express KDR that is phosphorylated, independent of grade." (PMID 17505508, 2007). "Coexpression of ligand and receptor in the tumour epithelium was most frequently found for the VEGF-C/Flt-4 combination (87% of cases), followed by the combinations of VEGF-C/KDR (51%), ET-1/ETAR (37%), ET-1/ETBR (26%), and VEGF-A/KDR (25%)." (PMID 15841074, 2005). "Vascular endothelial growth factor-A expression is elevated in tumours in response to a variety of stimuli, and its activity is largely restricted to vascular endothelial cells via two high-affinity receptors, Flt-1 (VEGF-R1) and KDR/Flk-1 (VEGF-R2)." (PMID 14612898, 2003). "In addition, KCNN4 demonstrates a negative correlation with CD160, KDR, and KIR2DL1, which are associated with NK and T‐cell activation, as well as tumour angiogenesis." (PMID 40952239, 2025). "Thus, the G5/PDGFRA subgroup contains tumors with an amplification of PDGFRA with or without neighboring KIT and KDR RTK genes from the 4q12 chromosomal locus, and more rarely, a tumor with PDGFRA activating mutations without amplification." (PMID 38254850, 2024). "Additionally, the 6 markers (KDR, CXCR6, STAT5A, MPL, NFATC3, and TLR6) we found to be downregulated in our late-recurring tumor samples are also biologically relevant to functional T-cell activity, which helps explain their expression and function in this context." (PMID 36195959, 2022). "Although persistent AXL/GAS6 co-overexpression and acquired MERTK and KDR overexpression did not accelerate tumor xenograft growth rate, other concurrent phenotypic changes might nonetheless bear on disease progression." (PMID 34292953, 2021). "However, VEGF-A overexpression alone is not sufficient to augment tumor angiogenesis and requires additional angiogenic mediators such as, presumably, KDR." (PMID 33889304, 2021). "The few cases of remarkable responders to angiogenesis inhibitors where translational correlative data attribute the responses to alterations in angiogenesis genes such as KDR in the tumor cells rather than affecting the normal endothelial cells in the microenvironement." (PMID 33931674, 2021). "The kinase insert domain receptor (KDR, a type IV receptor tyrosine kinase), also known as vascular endothelial growth factor receptor 2 (VEGFR-2), is largely recognized as a potent therapeutic molecular target for the development of angiogenesis-related tumor treatment." (PMID 34685441, 2021). "Therefore, new treatment approaches of VS with severe PTBE may lie in the reduction of VEGF secretion or the blockage of its receptors (e.g., flk1 and KDR), as they may reduce tumor neovascularization, tumor growth capacity, and tumor invasion capacity." (PMID 34434159, 2021). "Furthermore, APC (p < 0.0001), ASXL1 (p < 0.0001), DNMT3B (p = 0.001), PARP4 (p = 0.002), MET (p = 0.01), TOP1 (p = 0.01), KDR (p = 0.01), SRC (p = 0.01), PAK1 (p = 0.015), ALK (p = 0.02), and MYC (p = 0.03) alterations were found to be more common in tumor samples from AO mCRC patients." (PMID 33194656, 2020). "Angiogenesis-related genes (FLT1, KDR, SPARC, INSR, ANGPT2, and FLT4) and MHC-I molecules (HLA-A, HLA-B, HLA-C, HLA-E, and HLA-F) were highly expressed in cluster 3 ECs, indicating that the cells may function as antigen-presenting cells and promote tumor parenchymal angiogenesis." (PMID 37533434, 2023). "However, extensive mutational analysis of tumor genes could not identify predictive markers of regorafenib efficacy, including among genes involving in angiogenesis (FLT1, FLT2, FLT3, FLT4, KDR, TEK (TIE2), and VHL)." (PMID 33322802, 2020). "One can hypothesize that comparative downregulation of KDR (and perhaps, angiogenesis in general) in the primary tumor might impart selection pressure for invasion leading to upregulation of ICAM1 that reflects a tumor's potential to establish a metastatic lesion in a draining lymph node." (PMID 16780590, 2006).
tumor (continued). "The results presented here show the lack of VEGFA expression in tumor endothelial cells and disclose the role of VEGFA/KDR signaling in neo-vascularization of cRCC." (PMID 39000466, 2024). "Of note, PDGFRA and KDR are not contiguous in the 4q12 amplicon, and the intermediate gene KIT was also found as singularly amplified in a subpopulation of one tumor." (PMID 37610648, 2023). "In CRLM patients, NRAS, FGF1, and KDR mRNA and protein were expressed at higher levels in metastatic than in CRC primary tumor and adjacent noncancerous tissue (p < 0.05)." (PMID 38201598, 2023). "Although, the majority of tumor samples showed no CNA of ALK, PDGFRA, VEGFR2/KDR, FGFR1, and to a lesser extent of MET in both primary and recurrent samples, the concordance of CNA status varied substantially in the subset of cases with alterations." (PMID 30894200, 2019). "VEGF is produced and secreted by tumour cells and binds to the VEGF receptor (VEGFR/KDR), which is primarily expressed on non-tumourigenic endothelial cells (ECs) that line the inner side of blood vessels." (PMID 28487489, 2017). "In the current study, the expression of both VEGF receptors (VEGF-R), KDR and FLT1, on EVs was found to be similarly high in all patient sub-groups compared to HC and was not affected by tumor existence or exposure to chemotherapy." (PMID 28968987, 2017). "In contrast, the anti-KDR peptide did not bind to murine 4T1 and human MDA-MB-231 tumour cells but did bind to HUVEC cells, where these are known to express functional KDR." (PMID 15655556, 2005). "As expected, neither peptide induced apoptosis of these tumour cells (data not shown), demonstrating that the anti-NP1 and anti-KDR peptides only induce apoptosis in NP-1-positive or KDR-positive cells, respectively." (PMID 15655556, 2005). "However, three SNPs found in genes such as ALK, KDR, and ABL1 in the HBL tumor in this study were not reported in UCSC, COSMIC, and ClinVar databases." (PMID 37273678, 2023). "Quantitative RT-PCR analysis of 8 tumor xenograft-derived cell lines showed that none had lost expression of either GAS6 or AXL; in fact, 6 of 8 had acquired significantly increased expression of MERTK (also activated by Gas6) and KDR." (PMID 34292953, 2021). "Similarly, gene expression of EPHA2, KDR, LAMC2, MMP1, and MMP14 did not vary between tumours of mice treated without and with aspirin." (PMID 32246008, 2020). "Anti-KDR peptides however did not induce apoptosis of 4T1 and MDA-MB-231 tumour cells." (PMID 15655556, 2005). "Expression of full-length forms of the VEGF/PLGF receptors KDR and Flt-1 were reduced (p = 0.0254 and p = 0.0348, respectively) in CSCC relative to NHS, whereas expression of the alternatively spliced decoy receptor sFlt-1 was indistinguishable in tumor and control samples (p = 0.17)." (PMID 35878392, 2022).